PINK1 (PTEN induced kinase 1)
Diseases named in the same sentence as PINK1 in open-access papers (continued):
Sharing a sentence is not in itself a finding about the gene and the disease.
Alzheimer disease (continued). "Moreover, PINK1 levels in peripheral blood and cerebrospinal fluid of patients with multiple sclerosis or Alzheimer’s disease were markedly heightened, as compared to controls." (PMID 40979207, 2025). "This study may provide potential interventions centered on the regulation of PINK1–Parkin-dependent mitophagy and offer therapeutic strategies for the treatment of Alzheimer’s disease." (PMID 36982968, 2023). "There is evidence that altered PINK1-Parkin-related mitophagy may be involved in the pathogenesis of neurodegenerative diseases such as Alzheimer’s disease (AD) and Parkinson’s disease (PD)." (PMID 35184140, 2022). "Moreover, blood PINK1 may at least partially stem from the central nervous system, given that PINK1 can exist in the cerebrospinal fluid of humans with multiple sclerosis or Alzheimer’s disease." (PMID 40979207, 2025). "In addition, in a mouse model of Alzheimer’s disease (AD), it has been reported that the expression of the mitochondrial transport and dynamics regulator Miro2, which is degraded through PINK1/Parkin-dependent mitophagy, was decreased in Nestin-positive cells of the hippocampus." (PMID 36816109, 2023). "Additionally, several studies found that SIRT1/FoxO1 signaling could be activated by physical exercise to improve PINK1/PARKIN-mediated mitophagy in Alzheimer’s disease." (PMID 37629033, 2023). "Not withstanding this explanation, impaired PINK1 function might also render other neurons more susceptible to oxidative stress, suggesting that other neurodegenerative diseases (e.g., Alzheimer disease) might progress at a faster rate when PINK1 is mutated." (PMID 17638420, 2007). "The mitochondrial dynamics and mitophagy are also impaired during thedevelopment of Alzheimer’s disease.This is evidenced by alterations in the expression of the ATG5, Beclin1, LC3A,LC3B, PINK1, TERT, BCL2, and BNIP3L genes detected in a mouse model of AD." (PMID 41479568, 2025). "HIIT ameliorates cerebral neurodegeneration by upregulating hippocampal PINK1, Parkin, and BDNF proteins, promoting AMP-dependent protein kinase expression, and reducing amyloid-β protein accumulation in Alzheimer’s disease models." (PMID 40035032, 2025). "Recently, it was reported that Urolithin A reverses memory impairment through PINK1-, PDR1-, or DCT1-dependent mitophagy in both amyloid-β (Aβ) and tau C. elegans models of Alzheimer’s disease." (PMID 32274386, 2020). "Of note, PINK1 protein levels were found increased in human postmortem brain with normal aging, but not in brains with Alzheimer disease, suggesting that indeed different molecular mechanisms are at play." (PMID 39912496, 2025). "It presents data on the effectiveness of using comprehensive panels of molecular biomarkers in clinical practice, including β-amyloid, CD34, claudin, DRP1, endothelin-1, NF-kB, PINK1, RAGE, S100, α-synuclein, and tau protein, in patients with Alzheimer’s disease (AD) and vascular dementia (VD)." (PMID 41516246, 2025). "(A, B) Double immunofluorescence staining showing the distribution of PTEN-induced kinase 1 (PINK1) and Aβ (A), and pUb and Aβ (B), within the cingulate gyrus brain region of Alzheimer's disease (AD) patients compared to similar brain regions from age-matched controls." (PMID 40742280, 2025). "As knowledge obtained using different PINK1 and PARKIN transgenic animal models is being gathered, growing evidence supports the contribution of mitophagy impairment to several human pathologies, including PD and Alzheimer’s diseases (AD)." (PMID 33168089, 2020).
pulmonary fibrosis (42 papers, 2015 to 2025). Chronic progressive interstitial lung disorder characterized by the replacement of the lung tissue by connective tissue, leading to progressive dyspnea, respiratory failure, or right heart failure. "In myofibroblasts, TGF-β1 can induce transcriptional inhibition for PINK1, and deficient mitochondrial targeting for mitophagy, contributing to the progression of pulmonary fibrosis." (PMID 38812059, 2024). "Next, to further confirm the molecular regulation of OGG1/PINK1 during pulmonary fibrosis, the loss- and gain-of function experiments were conducted in vitro." (PMID 38822247, 2024). "Deficiency of PINK1 disrupts mitochondrial homeostasis and facilitates the development of lung fibrosis." (PMID 38745204, 2024). "Impaired mitochondrial in alveolar type II cells are associated with the downregulation of PINK1 and defective mitophagy, making them susceptible to apoptosis and the development of lung fibrosis." (PMID 38812059, 2024). "For example, macrophage-derived TGF-β1 can restrain PINK1 expression in fibroblasts to inhibit mitophagy and promote lung fibrosis; whereas it induces epithelial cells to produce ROS, causing cell death and pulmonary fibrosis." (PMID 37582956, 2023). "A low expression of PINK1 has been associated with increased apoptosis, increased susceptibility to mitochondrial damage, stress, and to lung fibrosis, through what appears to be a TFG-beta-mediated process." (PMID 37759636, 2023). "Accordingly, inhibition of USP30 represents a potential actionable drug target for intervening the pathologies associated with PINK1/Parkin deficiency-induced mitophagy dysfunction, such as Parkinson’s disease and pulmonary fibrosis." (PMID 35308234, 2022). "Recent reports have suggested that PINK1 is down regulated during the pro-fibrotic response, increasing susceptibility to lung fibrosis." (PMID 35628458, 2022). "Reduced expression of PINK1 induces mitochondrial dysfunction and release of profibrotic factors in ATIIs, increasing the susceptibility to lung fibrosis." (PMID 35111363, 2022). "For example, lung epithelial dysfunction is linked to a defect in Pink1/Parkin and impaired mitochondrial quality control, found in idiopathic pulmonary fibrosis and experimental models of lung fibrosis." (PMID 34117280, 2021). "PINK1 deficiency was recently correlated with pulmonary fibrosis, and its impaired expression led to an accumulation of damaged mitochondria in lung epithelial cells from patients with IPF." (PMID 34887870, 2021). "Altogether, these data suggest that ATF3, via regulation of PINK1, has an important role in the AECIIs susceptibility to lung injury, senescence, and development of lung fibrosis." (PMID 29363258, 2018). "In the mouse model exposed to increasing ER stress by a viral infection, PINK1 deficiency results in the accumulation of damaged mitochondria increased cell apoptosis and increased susceptibility to lung fibrosis." (PMID 30042371, 2018). "In fact, recent studies in PINK1 null mice demonstrated high levels of TGFβ1 and susceptibility to pulmonary fibrosis." (PMID 26059457, 2015). "Pink1-deficient mice are more susceptible to developing pulmonary fibrosis in a bleomycin model, suggesting PINK1 may be necessary to limit fibrogenesis." (PMID 34887870, 2021). "Furthermore, bleomycin-induced lung fibrosis is augmented in Pink1 deficient mice and associated with less mitophagy, accumulation of dysmorphic mitochondria, and increased ER stress and AT2 apoptosis." (PMID 32218238, 2020). "In a bleomycin-induced pulmonary fibrosis oxidative stress study, mitochondrial dysfunction and M2 macrophage polarization were associated with PINK1/Parkin downregulation, while the promotion of mitophagy by PINK1 overexpression reversed the macrophage phenotype." (PMID 39940788, 2025). "Thus, inhibition of USP30 may represent an actionable target to correct the PINK1/Parkin defect-associated pathologies of pulmonary fibrosis." (PMID 35308234, 2022).
pulmonary fibrosis (continued). "Finally, Pink1-/- mice were more susceptible than control mice to bleomycin induced lung fibrosis." (PMID 25785991, 2015). "To demonstrate whether the transcriptional downregulation of PINK1 by TGFβ1 in normal human lung fibroblasts is recapitulated in animal models of pulmonary fibrosis, we exposed mice to 3 × 108 PFU of replication-deficient adenovirus encoding either GFP (AdGFP) or active TGFβ1 (AdTGFβ1)." (PMID 26059457, 2015). "Naringenin has also been found to regulate mitophagy and alleviate pulmonary fibrosis via the ATF3/PINK1 pathway." (PMID 40230412, 2025). "In mouse lung tissue, PINK1 knockdown in ATII cells resulted in mitochondrial enlargement and dysfunction, impairing mitochondrial autophagy and increasing susceptibility to lung fibrosis." (PMID 40230412, 2025). "In vivo studies have shown that PINK1-deficient mice develop similar mitochondrial abnormalities in ATII cells, leading to apoptosis and lung fibrosis." (PMID 40230412, 2025). "A link between disrupted epithelial cell respiration and pulmonary fibrosis has been previously reported in Pink1–/– mice exhibiting impaired bioenergetics and age-related spontaneous fibrosis." (PMID 40591409, 2025). "TH5487 administration effectively mitigated pulmonary fibrosis, M2 macrophage polarization, oxidative stress and mitochondrial dysfunction while promoted PINK1/Parkin-mediated mitophagy in lung tissues of BLM-induced mice, which was partly hindered by Mdivi-1." (PMID 38822247, 2024). "Decreased PINK1 in aging lungs leads to impaired mitophagy, promoting pulmonary fibrosis in young mice." (PMID 39758315, 2024). "Taken together, OGG1/PINK1/mitophagy axis in fibroblasts played a crucial role in regulating pulmonary fibrosis and the relevant macrophage polarization." (PMID 38822247, 2024). "The protective role of OGG1 inhibition against pulmonary fibrosis is archived partly via activating PINK1/Parkin mitophagy and retarding M2 macrophage polarization." (PMID 38822247, 2024). "Protective mechanisms also exist against lung fibrosis in vivo, for example, thyroid hormone can promote the expression of PINK1 and PGC-1α, resulting in the restoration of mitochondrial function." (PMID 38812059, 2024). "OGG1 inhibition protects against pulmonary fibrosis, which is partly via activating PINK1/Parkin-mediated mitophagy and retarding M2 macrophage polarization, providing a therapeutic target for pulmonary fibrosis." (PMID 38822247, 2024). "The deficiency of PINK1 or Parkin has been demonstrated to impair mitochondrial homeostasis and promote lung fibrosis, highlighting the importance of PINK1/Parkin-mediated mitophagy during pulmonary fibrosis." (PMID 38822247, 2024). "Accumulating evidence has confirmed the abnormal expression and the regulatory role of PINK1 in type II alveolar epithelial cells and lung tissues following pulmonary fibrosis, while PINK1/Parkin-mediated mitophagy in in vitro fibroblasts is rarely explored." (PMID 38822247, 2024). "In vivo, PINK1-deficient mice develop similarly dysmorphic, dysfunctional mitochondria in the AT2 cells and are susceptible to apoptosis and development of pulmonary fibrosis." (PMID 34354793, 2021). "We have previously shown that endoplasmic reticulum stress (ER stress) represses the PTEN inducible kinase 1 (PINK1) in lung type II alveolar epithelial cells (AECII) reducing mitophagy and increasing the susceptibility to lung fibrosis." (PMID 31170232, 2019). "Further studies into the AEC2 cell-specific role of PINK1 and mitophagy in the development of pulmonary fibrosis are required." (PMID 31358769, 2019). "Conditional type II lung epithelial cells ATF3 knockout mice are protected from severe lung fibrosis induced by bleomycin showing a better outcome measured by pro‐fibrotic, pro‐inflammatory, and senescence markers while preserving PINK1 expression in the lung." (PMID 29363258, 2018).
pulmonary fibrosis (continued). "TGF-β represses mitophagy in lung fibroblasts and inhibits PINK1 expression during pulmonary fibrosis in both a mouse model and in vitro analysis." (PMID 30042371, 2018). "Supporting this role of T4 signaling in PINK1-mediated mitochondrial homeostasis and mitophagy, the therapeutic effect of inhaled T3 in mouse models of lung fibrosis required an active PINK1 signaling pathway." (PMID 29459894, 2018). "Here, we demonstrate for the first time an age-related decline in autophagy and selective targeting of mitochondria for autophagic degradation, with reduced PINK1 expression, in animal models of pulmonary fibrosis." (PMID 26059457, 2015). "Further analyses of PINK1 knockout mice will better define the role of PINK1 in lung aging and pulmonary fibrosis." (PMID 26059457, 2015). "Our investigation is one of the first to address the role of PINK1, a serine/threonine kinase critical for mitochondrial clearance by autophagy, in pulmonary fibrosis." (PMID 25785991, 2015). "In accord with these findings, PINK1 expression appeared to be reduced in fibrotic lung tissue from bleomycin and a TGFβ1-adenoviral model of lung fibrosis." (PMID 26059457, 2015). "Accumulating evidence reviewed above strongly implicates mitochondrial ROS production, mtDNA damage, and mitochondrial dysfunction (in part due to PINK1 deficiency) in the pathophysiology of AEC apoptosis and pulmonary fibrosis." (PMID 26370974, 2015). "We set up a bleomycin (BLM)-induced mouse pulmonary fibrosis model, and demonstrated that TH5487, the small molecule OGG1 inhibitor, could attenuate pulmonary fibrosis, activate PINK1/Parkin mitophagy and reduce M2 macrophage polarization." (PMID 38822247, 2024). "Furthermore, naringin modulates the activating transcription factor 3/PTEN-induced kinase 1 (ATF3/PINK1) pathway and enhances mitophagy in lung tissues, resulting in the alleviation of bleomycin-induced idiopathic pulmonary fibrosis." (PMID 38399736, 2024). "It has been reported that PINK1 can be induced by TGF-β1 in pulmonary fibrosis." (PMID 35292112, 2022). "Emerging evidence indicates that PINK1/Parkin-mediated mitophagy plays an essential role in the pathogenesis of various kinds of aging-associated pulmonary disorders, such as chronic obstructive pulmonary disease (COPD) and idiopathic pulmonary fibrosis (IPF)." (PMID 35308234, 2022). "TGF-β1, a key cytokine for asthma-related pulmonary fibrosis, could induce lung epithelial cell mitochondrial ROS and stabilize the key mitophagy initiating protein PINK1." (PMID 35008429, 2021). "PINK1 (PTEN‐induced putative kinase 1) is a key regulator of mitochondrial homeostasis that is relatively depleted in aging lungs and in lung epithelial cells from patients with idiopathic pulmonary fibrosis (IPF), a disease linked with aging." (PMID 29363258, 2018). "The upregulation of PINK1 by thyroid hormone reversed bleomycin-induced lung fibrosis, which might be due to restoring mitochondrial function through mitophagy." (PMID 30042371, 2018). "This connection may be critical in devising strategies designed to augment PINK1 expression or inhibit ATF3 levels to lessen severity of pulmonary fibrosis, especially in the context of the aging lung." (PMID 29363258, 2018). "Furthermore, we found that TGFβ1 represses autophagy, mitochondrial recycling, and homeostasis in normal human lung fibroblasts during FMD and inhibits PINK1 expression during pulmonary fibrosis." (PMID 26059457, 2015). "More recently, two groups have established that PTEN-induced putative kinase 1 (PINK1) deficiency impairs AEC mitochondrial function in patients with IPF and PINK1-deficient mice have increased AEC intrinsic apoptosis and lung fibrosis following viral-induced ER stress or bleomycin exposure." (PMID 26370974, 2015).
pulmonary fibrosis (continued). "Studies have indicated that the mechanism of IPF primarily involved defective PINK1/Parkin-mediated mitophagy in AEC, leading to increased occurrence of mtDNA damage, apoptosis, and senescence; these abnormalities collectively led to increased susceptibility to pulmonary fibrosis." (PMID 39183973, 2024). "Consistently, the western blot assay revealed that protein expression of OGG1 was significantly increased in BLM group, while the protein expression of PINK1 and Parkin was significantly decreased, suggesting that OGG1/PINK1 mitophagy might be involved in the progression of pulmonary fibrosis." (PMID 38822247, 2024). "In previous studies, hypoxia can activate the PINK1/Parkin-mediated mitophagy pathway, selective activation of mitophagy might promote cell survival under hypoxic conditions, breast cancer, and pulmonary fibrosis." (PMID 36304416, 2022). "Furthermore, Pink1 depletion promoted lung fibrosis in young mice." (PMID 35599014, 2022). "Intriguingly, it has been reported that thyroid hormone induces PINK1 expression with concomitant mitophagy, which is responsible for normalizing mitochondrial morphological and functional integrity and for attenuating bleomycin-induced lung fibrosis development." (PMID 30386443, 2018). "Thus, the young age of Pink1-/- animals in our experiments may also be moderating the effect on lung fibrosis." (PMID 25785991, 2015). "In BLM-induced lung fibrosis models, TH5487 reduced oxidative stress, promoted PINK1/Parkin-mediated mitophagy, and alleviated mitochondrial dysfunction." (PMID 40230412, 2025). "Taken together, these findings confirmed that TH5487 treatment effectively reduced oxidative stress, promoted PINK1/Parkin-mediated mitophagy and attenuated mitochondrial dysfunction in BLM-induced pulmonary fibrosis mice." (PMID 38822247, 2024). "Additionally, ER stress in AECII cells inhibited PINK1-mediated mitophagy, leading to extracellular release of mtDNA, which activated toll-like receptor 9 (TLR9) and triggered transforming growth factor-β (TGF-β) secretion, further increasing susceptibility to pulmonary fibrosis." (PMID 39183973, 2024). "It is indicated that up-regulation of PTEN-induced putative kinase 1 (PINK1) can restrain silica-induced lung inflammation and lung fibrosis in mice." (PMID 36979471, 2023). "In BLM-induced pulmonary fibrosis, OGG1 was upregulated while PINK1/Parkin was downregulated." (PMID 38822247, 2024). "By knocking down PINK1 on mice ATII cells, the authors detected an increase in profibrotic factors as well as observing dysmorphic and dysfunctional mitochondria in the ATIIs that were more vulnerable to apoptosis and the development of lung fibrosis." (PMID 37759636, 2023). "Intriguingly, thyroid hormone does not alleviate the pathological process of pulmonary fibrosis in PINK1-knockout mice." (PMID 34354793, 2021). "Further demonstrating the importance of mitophagy in mediating IPF, a recent finding demonstrated a dysfunctional thyroid axis in IPF, and thyroid hormone administration increased Pink1 levels, attenuated AT2 apoptosis, and reduced lung fibrosis via a Pink1-dependent mechanism." (PMID 32218238, 2020). "Although Parkin has not yet been studied in lung fibrosis, given its close interaction with PINK1, it should be the subject of future investigations." (PMID 25785991, 2015). "It is well known that PTEN induced kinase 1 (PINK1) and Parkin are essential for the maintenance of mitochondrial quality through mitophagy activation, and PINK1/Parkin-dependent mitophagy has been identified as a potential target for the treatment of pulmonary fibrosis." (PMID 38822247, 2024). "Reduced PINK1 levels were also demonstrated in fibroblastic foci in IPF lungs, and TGF-β may have a role in PINK1 reduction, resulting in promotion and perpetuation of pulmonary fibrosis." (PMID 30386443, 2018).